RNU6-215P (RNA, U6 small nuclear 215, pseudogene)
Gene: Small nuclear RNA gene on chromosome 7 (5,180,061 to 5,180,162, forward strand). Ensembl gene ENSG00000202039.
Homologues: Orthologues: chimpanzee U6 (97% identical), rabbit U6 (83% identical), pig U6 (76% identical), rat U6 (75% identical), pig U6 (74% identical). Paralogues in human: RNU6-1181P (87% identical), RNU6-633P (87% identical), RNU6-39P (86% identical), RNU6-45P (86% identical), RNU6-1005P (85% identical), RNU6-1024P (85% identical), RNU6-10P (85% identical), RNU6-1227P (85% identical), RNU6-12P (85% identical), RNU6-13P (85% identical), RNU6-16P (85% identical), RNU6-31P (85% identical), and 1286 more.